DCAKD (dephospho-CoA kinase domain containing)
Synonyms: FLJ22955
Tractability: PROTAC: ubiquitination databases record sites on it; its protein half-life has been measured.
Gene: Protein-coding gene on chromosome 17 (45,023,338 to 45,061,131, reverse strand). Ensembl gene ENSG00000172992.
Subcellular location (Human Protein Atlas): Nucleoplasm
Pathways (Reactome):
Metabolism: Coenzyme A biosynthesis
Gene Ontology:
Molecular function: dephospho-CoA kinase activity; ATP binding
Biological process: coenzyme A biosynthetic process
Cellular component: membrane; mitochondrial outer membrane; cytoplasm
Genetic constraint (gnomAD): Loss-of-function variants: 16 observed, 20.87 expected, observed/expected ratio (o/e) 0.77, 90% interval 0.52 to 1.16. The upper end of that interval is the gene's LOEUF score, 1.16, which puts it in group 5 of 6, group 1 being the genes least tolerant of losing a copy. Missense variants: 301 observed, 335.54 expected, observed/expected ratio (o/e) 0.9, 90% interval 0.82 to 0.99. Synonymous variants: 130 observed, 139.85 expected, observed/expected ratio (o/e) 0.93, 90% interval 0.81 to 1.08.
Homologues: Orthologues: chimpanzee DCAKD (99% identical), macaque DCAKD (98% identical), dog DCAKD (91% identical), rabbit DCAKD (91% identical), mouse Dcakd (91% identical), rat Dcakd (90% identical), guinea pig DCAKD (83% identical), pig DCAKD (77% identical), tropical clawed frog dcakd (55% identical), zebrafish dcakd (53% identical), Drosophila melanogaster Dpck (38% identical), Caenorhabditis elegans T05G5.5 (36% identical). Paralogues in human: COASY (26% identical).
Diseases named in the same sentence as DCAKD in open-access papers:
DCAKD is named in the same sentence as 2 diseases in open-access papers, as found by Europe PMC text mining. Sharing a sentence is not in itself a finding about the gene and the disease.
DCAKD shares sentences with these, for which no sentence is quoted: melanoma (1 paper); Parkinson disease (1).